ATRX (ATRX chromatin remodeler)
Diseases named in the same sentence as ATRX in open-access papers (continued):
Sharing a sentence is not in itself a finding about the gene and the disease.
cancer (continued). "We assessed transcription-coupled histone chaperones ATRX and DAXX, and observed that both are overexpressed in most cancer cell lines relative to normal colon, ranging from three- to twentyfold excess protein." (PMID 25788983, 2015). "The same correlation between inactivation of the ATRX pathway and the ALT-like phenotype was observed in pediatric glioblastoma and several other cancers." (PMID 22829774, 2012). "The absence of the ATRX chromatin remodeling factor is the dominant prognostic marker in these types of cancer." (PMID 38674026, 2024). "There is indeed evidence that inducing aberrations within the ATRX gene does not necessarily cause ALT in different cell types and cancers." (PMID 37540673, 2023). "In SCLC, it can be observed that cancer gene alterations appear to be more frequent in women, the most consistent differences being observed in PTRD, CREBBP, GRM3, ATRX, NOTCH3, and PDE4DIP, while ATM appears to be altered in 5.26% of men, and no alterations were depicted in women." (PMID 35330454, 2022). "For example, while ATRX-deficient cancer cells seem to rely on RECQ5 for HR, normal untransformed cells do not use RECQ5 and rely completely on ATRX for HR." (PMID 34408777, 2021). "The dysregulation of above AS events in ATRX and MYBL2 are significantly related to mitosis and tumorigenesis in cancer patients, suggesting that MTA1 may regulate mitosis and tumorigenesis by targeting the AS of these two mitosis regulators." (PMID 32901005, 2020). "Loss of ATRX and DAXX is strongly related to alternative lengthening of telomeres (ALT), a process characteristic of cancer cells in which telomere length is retained through a non-telomerase-dependent mechanism." (PMID 32533344, 2020). "Mutations in the ATRX/DAXX chromatin remodeling complex have been observed in cancers and cell lines that use the ALT mechanism, suggesting that ATRX may suppress the ALT pathway." (PMID 31157162, 2019). "ATRX is mutated both in patients with the X-linked alpha thalassemia mental retardation syndrome (ATR-X syndrome), and in cancers that use a non-telomerase mechanism for lengthening their telomeres." (PMID 31546714, 2019). "Interestingly, also ATRX, a chromatin remodeling factor strongly downregulated in ALT cancer cells, was modulated in response to IR." (PMID 31336873, 2019). "Our results contribute to a growing body of literature that is revealing ATRX-independent functions of DAXX that may have important implications for viral restriction, cancer biology, and epigenetics." (PMID 30465651, 2018). "Despite the strong association between ATRX loss and ALT in cancer, prior studies have not observed ALT characteristics after ATRX knockout or knockdown, much like we have observed with the MOG-G-UVW and SF188 cell lines." (PMID 30226859, 2018). "As a small minority of ALT-cancer cells exhibit DAXX loss, rather than ATRX loss, we generated CRISPR-Cas9 mediated DAXX knockout clones in the HeLa LT cell line, both in the context of wildtype ATRX and ATRX knockout." (PMID 36940725, 2023). "However, some ALT cancers do not exhibit ATRX or DAXX mutations, so they are not essential to ALT cancer activation." (PMID 37046606, 2023). "In addition, another study showed that in mouse embryonic stem cells, although ATRX loss causes extensive genomic instability, it does not on its own cause ALT or cancer." (PMID 35087762, 2021). "However, the upstream regulator of ATRX and SMC5 remains unclear, while our study provided the emerging evidence that U50A suppresses these genes to hinder cancer cell mitosis." (PMID 34944924, 2021).
cancer (continued). "Cells lacking ATRX are also particularly sensitive to cell death caused by G4-stabilizing molecules, raising the possibility that these molecules will be a useful therapy for ALT cancers." (PMID 31546714, 2019). "Genetic mutations in ATRX, DAXX, and H3.3 have been detected in ALT positive cancers, however, a subset of ALT samples show loss of ATRX or DAXX protein expression or localization without evidence of genetic alterations suggesting additional uncharacterized defects in ATRX/DAXX/H3.3 function." (PMID 30214690, 2018). "We showed that overexpression of TPP1ΔOBRD, ATRX knockdown, DAXX deletion and TERT KO in telomerase-positive HTC75 cancer cells could promote ALT phenotypes by increasing APBs and C-circles, elongating telomeres and producing heterogeneous telomeres, which were very similar to ALT cells." (PMID 27578458, 2016). "There have been no reports of an increased incidence of cancer, ALT or otherwise, in individuals with ATRX mutations, but this may be because of the small number of such cases." (PMID 23185534, 2012). "Therefore, ATRX and DAXX may promote or inhibit malignant neoplasms, depending on the cancer type." (PMID 36428674, 2022). "ATRX KO induces ALT activation in the telomerase-negative cancer cells but, alone, is not sufficient to activate ALT in telomerase-positive cancer cells, in which it was necessary to also create gene KO of TERT through the CRISPR-Cas9 system to achieve comparable results." (PMID 36497228, 2022). "The authors go on to demonstrate that canonical ALT cells, likely due to their lack of functional ATRX, are equally sensitive to PolI inhibitors, suggesting that PolI inhibitors could be effective on a wide range of ALT cancers." (PMID 32039009, 2019). "However, knockdown of ATRX is not sufficient to trigger the ALT pathway in telomerase-positive cell lines or to directly activate ALT in normal somatic cells, implying the existence of other necessary contributing factors involved in activation of ALT in cancer cells." (PMID 27323951, 2016).
infection (26 papers, 2009 to 2025). The state of being infected such as from the introduction of a foreign agent such as serum, vaccine, antigenic substance or organism. "We found, as expected, that ATRX deficiency results in selective sensitivity to infection with ICP0-null HSV-1." (PMID 30745338, 2019). "However, ATRX has been implicated in the cellular response to DNA damage, and chromatin remodeling—processes which many viruses exploit during infection." (PMID 39869679, 2025). "Additionally, we observed the association of ATRX with viral gene promoters by 4 hr post infection." (PMID 30465651, 2018). "Recombinant HCMVs lacking the gene (UL82) encoding for pp71 show decreased viral major IE transcript and protein accumulation upon lytic infection of fibroblasts, and knockdown of ATRX increased viral IE protein accumulation from a pp71-null virus." (PMID 39236084, 2024). "During infection of ATRX-positive (SCR) cells, we visualized and quantitated fewer UL44-positive replication factories than during infections of ATRX-depleted cells." (PMID 39236084, 2024). "Infection of Daxx KO cells led to a significant reduction in ATRX and histone H3.3 colocalization at vDNA relative to infected NTC cells, demonstrating a Daxx-dependent mechanism of histone H3.3 enrichment at vDNA." (PMID 39185184, 2024). "Our work mechanistically defines the anti-viral effects of ATRX at the start of HCMV lytic infections." (PMID 39236084, 2024). "ATRX knockdown cells also showed an increase in IE1-positive cells during a Wild Type (WT) HCMV lytic infection." (PMID 39236084, 2024). "This experiment shows that ATRX-KD increases viral protein accumulation but cannot determine if ATRX knockdown cells were accumulating more viral proteins per cell, or if more cells were initiating infection." (PMID 39236084, 2024). "We then examined ATRX, an ND10 constituent that is not degraded but is dispersed upon PML degradation, to observe ATRX localization relative to eCFP-PML I in late infection." (PMID 37243155, 2023). "Alignment of the ChIP-seq reads revealed a dense distribution of H3 across the entire HSV genome in both ATRX-KO and Controls during infection." (PMID 33909709, 2021). "Of genes identified as down-regulated during infection, 92% of downregulated genes in Control cells were also downregulated in ATRX-KO cells." (PMID 33909709, 2021). "The same study also observed that DEK, a H3.3 chaperone that regulates H3.3 distribution to HIRA and ATRX/DAXX, associated with the viral genome for most of the first 6 h of infection." (PMID 33909709, 2021). "We showed recently that ATRX is dispensable for de novo deposition of H3 to HSV genomes after nuclear entry but restricted infection through maintenance of viral heterochromatin." (PMID 33909709, 2021). "We found that ATRX promotes reduced accessibility of viral DNA during infection, likely preventing access for factors necessary for viral gene expression and replication." (PMID 33909709, 2021). "When transcription was inhibited globally, we found that only a combinatorial depletion of ATRX/HIRA/ASF1A resulted in a significant decrease in total H3 deposition by 4 h post infection (hpi), suggesting multiple pathways for chromatinizing naked DNA." (PMID 33909709, 2021). "Depletion of a chromatin remodeler ATRX also increases mRNA levels of all genes in three HSV-1 kinetic groups at any time of infection up to 8 hours." (PMID 31725813, 2019). "ATRX, PML, and IFI16 are associated with the HSV-1 genome within the first hour after infection, and initial heterochromatin formation is dependent on ATRX." (PMID 31500286, 2019). "Here we report on the mechanisms of viral gene restriction mediated by ATRX during the first 8 hours of infection." (PMID 30465651, 2018).
infection (continued). "We used herpes simplex virus with bioorthogonally labeled genomes to detect host factors recruited to viral DNA shortly after its nuclear entry and found that the cellular IFI16, PML, and ATRX proteins colocalized with viral DNA by 15 min post infection." (PMID 30465651, 2018). "HSV-1EdU infection of shCtrl or shATRX cells demonstrated that depletion of ATRX led to a distinct population of viral genomes with a reduced colocalization frequency with PML (left-hand dotted box)." (PMID 29309427, 2018). "Conversely, the heterochromatin maintenance mechanism mediated by ATRX appears to act as a critical restrictive hurdle to productive infection." (PMID 30465651, 2018). "(C) ATRX-KO and Control cells were treated with α-amanitin (2 μg/mL) from 16 hr prior to infection until time of harvest." (PMID 30465651, 2018). "(B) ATRX-KO and Control cells were treated with flavopiridol (flavopiridol; 1 μM) from 1 hr prior to infection until time of harvest." (PMID 30465651, 2018). "For instance, a PML-associated ATRX-DAXX complex has been demonstrated to chromatinize and transcriptionally repress herpesviruses during infection, while a HIRA-UBN1 complex is thought to coordinate senescence-associated heterochromatinization." (PMID 25665578, 2015). "Daxx forms a chromatin remodeling complex with ATRX and ATRX has been implicated in the transcriptional repression of both HSV-1 and HCMV during the early steps of infection." (PMID 22102817, 2011). "It was reported previously that infection with in1316 resulted in the dispersal of ATRX at 3 h pi, a time at which YFPpp71 and Daxx remained at ND10 in a punctate distribution." (PMID 19473490, 2009). "In summary, these data clearly identified the ND10 proteins PML, hDaxx and ATRX as cellular restriction factors responsible for silencing of HCMV IE gene expression directly upon infection." (PMID 21994592, 2009). "Recent studies indicate that pp71 stimulates the release of ATRX, a cell protein with chromatin remodelling activity, from ND10 in a very early event after infection, suggesting that ATRX is an important component of the cellular intrinsic defences to HCMV." (PMID 19473490, 2009). "Thus, it is apparent that ATRX and DAXX have distinct roles in early transcriptional regulation and that ATRX promotes transcription upon initial infection." (PMID 41012597, 2025). "We propose that ATRX acts in a pro-transcriptional capacity early in infection, when the genome is largely nucleosome-free, but may adopt a repressive function as the genome becomes more chromatinized." (PMID 41012597, 2025). "In summary, our study underscores ATRX’s critical role in modulating HCMV lytic infections." (PMID 39236084, 2024). "Notably, ATRX has been reported to promote the stability of viral heterochromatin upon infection of fibroblasts." (PMID 39185184, 2024). "Conversely, ATRX overexpression decreased IE protein accumulation during WT HCMV lytic infection." (PMID 39236084, 2024). "It is possible that DAXX is restrictive while in complex with ATRX but at a later stage of infection, after dispersion of PML-NBs and degradation of ATRX, DAXX may promote HSV gene expression or replication." (PMID 30465651, 2018). "Furthermore, we found that many of IFIX interactions were lost following infection, including PML and its associated proteins (DAXX, ATRX, HIRA, etc.)." (PMID 25665578, 2015). "In essence, the low levels of GATA-2 in more differentiated cell types that HCMV lytically infects may result in the additional requirement of IE72 activity against hDaxx:ATRX to promote LUNA gene expression during lytic infection." (PMID 23736881, 2013). "However, during lytic infection, depletion of hDaxx:ATRX complex is required for LUNA gene expression to occur." (PMID 23736881, 2013).
infection (continued). "Furthermore, RNA interference (RNAi) studies have shown that knockdown of Daxx or ATRX can result in a higher infection level of HCMV and also relieve the infection defect of mutant HSV deficient in disrupting PML-NB." (PMID 22102817, 2011). "Thus, ATRX may contribute to transcriptional repression during later stages of lytic infection as previously reported." (PMID 41012597, 2025). "However, viral heterochromatin stability required ATRX from 4 to 8 hr post infection." (PMID 30465651, 2018). "ATRX limits the accumulation of human cytomegalovirus (HCMV) Immediate Early (IE) proteins at the start of productive, lytic infections, and thus is a part of the cell-intrinsic defenses against infecting viruses." (PMID 39236084, 2024). "More importantly, the eCFP-PML I dots were colocalized with ATRX in the nucleus, indicating the reformation of ND10-like structures late in the RHG105 infection (pink arrowheads)." (PMID 37243155, 2023). "Westernblot showed when the multiplicity of infection (MOI) of lentivirus was 50 in MCF-7 cell, the expression of ATRX was increased significantly." (PMID 38126976, 2023). "DAXX depletion has consistently resulted in comparatively smaller increases in viral yield than ATRX depletion, and DAXX has recently been reported to have potential roles in viral activities during late infection." (PMID 33909709, 2021). "For example, HSV-1 also expresses high levels of microRNA (miR)-H1 during infection, and one of its targets is the 3′ UTR of ATRX." (PMID 30745338, 2019). "ATRX-KO and Control cells were pretreated with PAA for 1 hr prior to infection and maintained for the duration of the experiment." (PMID 30465651, 2018). "By 90 min post infection, ICP0 was observed to localize to ATRX foci that also colocalized with HSV genomes." (PMID 30465651, 2018). "Early during infection in fibroblasts, the viral tegument protein pp71 traffics to the PML-NBs in the nucleus and displaces ATRX, then induces sumoylation and ubiquitin-dependent degradation of Daxx, resulting in IE expression." (PMID 30127257, 2018). "Along with nuclear DNA sensor IFI16, we detected ATRX and PML recruitment to viral DNA by 15 min post infection (mpi), almost immediately upon nuclear entry." (PMID 30465651, 2018). "Both the ATRX hypomorph and knockdown showed similar increases in IE (IE1 and IE2) transcript accumulation after infection with HCMV strain AD169 at an MOI of 0.1, as expected from previous observations of increased IE protein accumulation after ATRX knockdown." (PMID 39236084, 2024). "ATRX knockdown decreased H3.3 and H3K9me3 occupancy at the AD169 MIEP and decreased the occupancy of total histone H3, H3.3, and H3K9me3 at the MIEP during TB40/E infections." (PMID 39236084, 2024). "MAMDC2-AS1 was not significantly upregulated in ATRX-KO cells before or during infection as compared to Control cells." (PMID 33909709, 2021). "ChIP of HSV-1 DNA in ATRX depleted cells indicated that histone H3K27me3 occupancy on the ICP27 and ICP8 gene promoters is not significantly affected up to 4 hours of infection, but reduced to about half at 8 hours after infection." (PMID 31725813, 2019). "Cells treated with siIFI16 and infected at a multiplicity of infection (MOI) of 5 with HSV-EdC showed no significant reduction in ATRX colocalization with viral genomes at 30mpi." (PMID 30465651, 2018). "During replicative infection, the MIEP is initially silenced following formation of a repressive chromatin structure by the nuclear domain 10/promyelocytic leukemia nuclear body (PML-NB) proteins Daxx and ATRX." (PMID 30127257, 2018). "From these results we concluded that ATRX promotes maintenance of stable viral heterochromatin during infection and delays the onset of viral DNA replication but is not uniquely required for the de novo formation of chromatin on input viral genomes." (PMID 30465651, 2018).